CYP2A6 (cytochrome P450 family 2 subfamily A member 6)
Description:
Exhibits a high coumarin 7-hydroxylase activity. Can act in the hydroxylation of the anti-cancer drugs cyclophosphamide, ifosphamide and tegafur. Competent in the metabolic activation of aflatoxin B1. Constitutes the major nicotine C-oxidase. Acts as a 1,4-cineole 2-exo-monooxygenase. Possesses low phenacetin O-deethylation activity.
Synonyms: CYP2A3; CPA6; CYP2A; CYPIIA6; P450C2A; P450PB
Tractability: Small molecule: a structure with a bound ligand is known; a high-quality ligand is known; it has a high-quality binding pocket; it belongs to a druggable protein family. Antibody: UniProt places it where antibodies can reach, with medium confidence. PROTAC: its protein half-life has been measured; a small molecule that binds it is known.
Target class: Cytochrome P450 2A6; Cytochrome P450; Enzyme; Cytochrome P450 family 2; Cytochrome P450 family 2A
Safety:
Unwanted effects reported when the protein is acted on. In parentheses: how it was acted on, where the effect was seen, and who reports it.
nicotine dependence (source: ClinPGx)
Gene: Protein-coding gene on chromosome 19 (40,843,533 to 40,850,450, reverse strand). Ensembl gene ENSG00000255974.
Subcellular location: Endoplasmic reticulum membrane; Microsome membrane
Pathways (Reactome):
Metabolism: CYP2E1 reactions; Xenobiotics
Gene Ontology:
Molecular function: coumarin 7-hydroxylase activity; enzyme binding; heme binding; protein binding; arachidonate epoxygenase activity; oxidoreductase activity, acting on paired donors, with incorporation or reduction of molecular oxygen, reduced flavin or flavoprotein as one donor, and incorporation of one atom of oxygen; iron ion binding; monooxygenase activity; oxidoreductase activity, acting on paired donors, with incorporation or reduction of molecular oxygen
Biological process: coumarin catabolic process; coumarin metabolic process; steroid metabolic process; xenobiotic catabolic process; xenobiotic metabolic process; epoxygenase P450 pathway
Cellular component: cytoplasmic microtubule; cytoplasm; endoplasmic reticulum membrane
Genetic constraint (gnomAD): Loss-of-function variants: 27 observed, 42.38 expected, observed/expected ratio (o/e) 0.64, 90% interval 0.47 to 0.88. The upper end of that interval is the gene's LOEUF score, 0.88, which puts it in group 3 of 6, group 1 being the genes least tolerant of losing a copy. Missense variants: 628 observed, 624.88 expected, observed/expected ratio (o/e) 1, 90% interval 0.94 to 1.07. Synonymous variants: 238 observed, 235.69 expected, observed/expected ratio (o/e) 1.01, 90% interval 0.91 to 1.12.
Homologues: Orthologues: macaque CYP2A24 (93% identical), macaque CYP2A29 (92% identical), macaque CYP2A23 (90% identical), dog CYP2A13 (89% identical), pig CYP2A19 (87% identical), dog CYP2A7 (86% identical), mouse Cyp2a5 (85% identical), rat Cyp2a3 (85% identical), rabbit CYP2A10 (85% identical), mouse Cyp2a4 (84% identical), mouse Cyp2a12 (70% identical), mouse Cyp2a22 (70% identical), and 2 more. Paralogues in human: CYP2A7 (94% identical), CYP2A13 (94% identical), CYP2F1 (52% identical), CYP2C19 (51% identical), CYP2B6 (50% identical), CYP2C8 (49% identical), CYP2C9 (49% identical), CYP2C18 (48% identical), CYP2S1 (47% identical), CYP2E1 (46% identical), CYP2J2 (39% identical), CYP2U1 (38% identical), and 3 more.
Diseases named in the same sentence as CYP2A6 in open-access papers:
CYP2A6 is named in the same sentence as 93 diseases in open-access papers, as found by Europe PMC text mining. Sharing a sentence is not in itself a finding about the gene and the disease. The quoted sentences say what the papers report.
lung carcinoma (52 papers, 2003 to 2025). "If these hybrids result in loss of function of CYP2A6, the risk of lung cancer development should be re-evaluated to account for these SVs." (PMID 41272073, 2025). "CYP2A6 genotypes are associated with variations in enzymatic activity and increase the risk of developing tobacco-related diseases, including lung cancer." (PMID 41272073, 2025). "CYP2A6 metabolizes nicotine into cotinine, thereby influencing smoking behaviors and lung cancer risk." (PMID 41249771, 2025). "Of the CYP2A6 alleles observed above, all twelve alleles were associated with lung cancer (alveolar cell carcinomas), susceptibility to tobacco addiction, Letrozole toxicity and coumarin resistance." (PMID 36556234, 2022). "In this cohort, CYP2A6 genotype predicted P450 2A6 activity, measured as the urinary ratio of 3′-hydroxycotinine to cotinine, and the risk of lung cancer was 30% lower for predicted poor metabolizers compared with other groups." (PMID 33932402, 2021). "In colorectal tumors and lung cancers, the expression of CYP2A6 is upregulated and associated with the degree of malignancy of the tumor." (PMID 33455085, 2021). "Many, but not all epidemiological studies have reported an association between CYP2A6 variants and the risk of a smoker to develop lung cancer." (PMID 33932402, 2021). "In a case control study in light smokers of European ancestry, fewer lung cancer cases carried one or more CYP2A6 variant (∗2, ∗4, ∗9, or ∗12), than did controls." (PMID 33932402, 2021). "CYP2A6 is primarily involved in the metabolism of nicotine and hence is associated with tobacco-related disorders including lung cancer." (PMID 33809117, 2021). "Only a handful of studies in non-Asian populations have found a significant relationship between CYP2A6 genotype and lung cancer risk." (PMID 33932402, 2021). "The relative risk of lung cancer is significantly influenced by smoking dose, and CYP2A6 variants that affect smoking would be expected to influence the risk." (PMID 33932402, 2021). "In contrast, much evidence has established a strong connection from CYP2A6 genotype to nicotine metabolism to smoking dose and lung cancer risk." (PMID 33932402, 2021). "We also describe epidemiology studies that establish the contribution of nicotine metabolism and CYP2A6 genotype to lung cancer risk, particularly with respect to specific racial/ethnic groups, such as those with Japanese, African, or European ancestry." (PMID 33932402, 2021). "The authors suggested, as others have, that the additional effect of CYP2A6 genotype on lung cancer risk was due to a reduction in P450 2A6–mediated bioactivation of NNK." (PMID 33932402, 2021). "In a study of similar design in Singapore Chinese, CYP2A6 genotype was also associated with both total nicotine equivalent levels and a reduced risk of developing lung cancer." (PMID 33932402, 2021). "In a study of Shanghai Chinese, the direct relationship of CYP2A6 genotype to nicotine metabolism, smoking dose, and lung cancer risk was demonstrated." (PMID 33932402, 2021). "The analysis, involving 4385 lung cancer cases and 4142 controls, suggested that CYP2A6 polymorphism significantly reduces the risk of lung cancer (pooled OR=0.39; 95% CI: 0.27–0.56), with homogeneity observed across studies (χ2=2.49, p=0.96, I2=0%)." (PMID 32547353, 2020). "A comprehensive search of different databases was used to yield the most relevant results and incorporated the available epidemiologic evidence to explore the relationship between the CYP2A6*4 whole-gene deletion polymorphism and the risk of lung cancer." (PMID 32547353, 2020). "Current evidence from the case-control studies suggests that the CYP2A6 whole-gene deletion polymorphism decreases the risk of lung cancer." (PMID 32547353, 2020). "We performed this meta-analysis to determine the association between whole-gene CYP2A6 deletion polymorphism (CYP2A6*4) and lung cancer risk." (PMID 32547353, 2020).
lung carcinoma (continued). "Six studies did not stratify the smoking status to assess the association between CYP2A6 polymorphism and lung cancer." (PMID 32547353, 2020). "The pooled OR estimates showed that the CYP2A6*4 whole-gene deletion polymorphism significantly reduced the risk of lung cancer (pooled OR=0.39; 95% CI: 0.27–0.56)." (PMID 32547353, 2020). "The evidence from the case-control studies included in the present meta-analysis shows that people with CYP2A6*4 whole-gene deletion have a decreased risk of lung cancer." (PMID 32547353, 2020). "Many reports have demonstrated that CYP2A6 variants that exert reduced enzymatic activity are associated with lower lung cancer risk." (PMID 31430927, 2019). "One strong finding that has emerged is the important role of CYP2A6-mediated nicotine metabolism in predicting smoking intensity (the nicotine uptake from each cigarette), carcinogen exposure and lung cancer risk." (PMID 30155522, 2018). "In the present study, all lung cancer cases, with CYP2A6*2 and *9 polymorphisms were diagnosed as NSCLC, 3 of them were adenocarcinoma." (PMID 29724170, 2018). "The tested polymorphisms are not affected by age and our aim was to to assess the contribution of the CYP2A6*2 and CYP2A6*9 gene polymorphisms and tobacco smoking in the risk of lung cancer." (PMID 29724170, 2018). "Considerable studies have reported the role of CYP2A6 genetic polymorphisms in lung cancer risk with some contradictory results in different populations from ethnic variation." (PMID 29724170, 2018). "A lack of statistical power in ethnic/racial groups with lower frequencies of CYP2A6 null alleles has made establishing an association between CYP2A6 genotype, smoking dose or intensity, and lung cancer in these groups challenging." (PMID 30155522, 2018). "The purpose of the current study is to assess the contribution of the CYP2A6*2 rs1801272 and CYP2A6*9 rs28399433 gene polymorphisms and tobacco smoking in the risk of lung cancer in an Egyptian population." (PMID 29724170, 2018). "Ariyoshi & colleagues, demonstrated that individuals homozygous for the CYP2A6*1A allele (*1A/*1A) have the highest risk for tobacco-related lung cancer in Japanese male smokers." (PMID 29724170, 2018). "Several studies have reported the role of CYP2A6 genetic polymorphisms in smoking and lung cancer risk with some contradictory results in different populations." (PMID 29724170, 2018). "We conducted a case-control study to assess the contribution of the CYP2A6*2 rs1801272 and CYP2A6*9 rs28399433 gene polymorphisms and tobacco smoking in the risk of lung cancer in an Egyptian population." (PMID 29724170, 2018). "Discordant results have been demonstrated on the association of CYP2A6 genetic polymorphisms and lung cancer risk." (PMID 29724170, 2018). "Whereas, in the present prospective study of five racial/ethnic groups (with a range of frequencies for CYP2A6 variant alleles), we observed a significant association for CYP2A6 activity with lung cancer risk, even after adjusting for TNE." (PMID 28542511, 2017). "A recent publication from the Shanghai Men’s Health study reported that CYP2A6 genetic variants confirmed to be associated with a reduced enzymatic activity were associated with a decreased risk of lung cancer (odds ratio [OR] = 0.64; p = 0.03)." (PMID 28542511, 2017). "Together these findings highlight the possibility for a more direct role of CYP2A6 in lung cancer risk." (PMID 29194389, 2017). "Some studies reported that, consistent with our findings, low CYP2A6 activity variants were associated with a reduced risk of lung cancer, possibly only in smokers." (PMID 28542511, 2017). "In an earlier report, using a genome-wide association study approach in two independent studies, we showed that the top six CYP2A6 variants associated with lung cancer risk (n = 13,479 cases and 43,218 controls) were also associated with CYP2A6 activity." (PMID 28542511, 2017).
lung carcinoma (continued). "Previous studies have investigated the association of functional variants in the CYP2A6 gene with lung cancer risk." (PMID 28542511, 2017). "Alternatively, when further adjusting for TNE, log-CYP2A6 activity remained significantly associated with lung cancer (HR per unit increase in log-CYP2A6 activity = 1.46; 95% CI: 1.08–1.98)." (PMID 28542511, 2017). "There are many tobacco-related diseases, which have been associated with variation in CYP2A6, including lung cancer, chronic obstructive pulmonary disease, diabetes, abdominal obesity, and others." (PMID 29194389, 2017). "Two other CYPs associated with lung cancer risk due to cigarette smoking, i.e., CYP2A6 and CYP2A13, displayed moderate up-regulation (FC of 9.5 and 8.9, respectively) in differentiated ALI-PBEC." (PMID 27738743, 2017). "The CYP2A6 gene polymorphism has been found to be associated with the development of lung cancer, and CYP2A6 has emerged as a novel candidate oncogene; however, CYP2A6 amplification has not been investigated." (PMID 27902773, 2016). "rs1137115 was nominally significantly associated with lung cancer in a meta-GWAS database, adding to existing evidence that other CYP2A6 variants contribute to lung cancer risk." (PMID 26132489, 2015). "The known SNP marker rs28399433 (low risk of lung cancer among smokers) was found here within the human CYP2A6 gene (nicotine oxidase; synonyms: xenobiotic monooxygenase, polypeptide 6 of subfamily A of family 2 of cytochrome p450)." (PMID 26516624, 2015). "SNPs near CYP2A7 and CYP2A6 on chromosome 19 have been associated with lung cancer, cigarette smoking, and COPD." (PMID 26634245, 2015). "We found evidence that variation in CYP2B6 influences lung cancer risk with a similar magnitude to CYP2A6 and that variation in these genes influences lung cancer risk independently." (PMID 23591849, 2013). "It was previously shown that the CYP2A6 alleles are associated with smoking-related lung cancer in a Japanese population." (PMID 23049750, 2012). "The CYP2A6 rs1801272 polymorphism was significantly associated with a decreased lung cancer risk in squamous cell carcinoma cases (OR = 0.47, 95%CI = 0.27–0.81, ptrend = 0.007; test for heterogeneity by histology: pheterog = 0.045)." (PMID 19479063, 2009). "As a result, individuals with these mutations have reduced nicotine cravings, a higher likelihood of quitting smoking or maintaining lower smoking rates, as well as a lower risk of developing lung cancer, compared to those with normal CYP2A6 enzymatic activity." (PMID 40384578, 2025). "Genotypic polymorphisms of CYP2A6 have a significant impact on smoking behavior–individuals with low CYP2A6 activity score consume fewer cigarettes per day and over their lifetime and have a lower risk of lung cancer." (PMID 38440181, 2024). "Genetic variants of CYP2A6 are associated with changes in the activity of the CYP2A6 enzyme, which influences smoking effects and the rate at which some tobacco-specific carcinogens are metabolized, which subsequently determines the incidence of lung cancer." (PMID 36289279, 2022). "CYP2A6 genotype is associated with lung cancer risk in smokers." (PMID 33932402, 2021). "While this may be one mechanism by which CYP2A6 genotype is associated with lung cancer risk, the direct relationship of NNK bioactivation to lung cancer risk has not been demonstrated." (PMID 33932402, 2021). "CYP2A6 genotype was also associated with lung cancer in two African American cohorts." (PMID 33932402, 2021). "This review provides a comprehensive overview of nicotine metabolism; a summary of the use of biomarkers to define smoking dose; and an overview of molecular epidemiology studies of CYP2A6 genotype, nicotine metabolism, and the risk of lung cancer across different racial/ethnic groups." (PMID 33932402, 2021).
lung carcinoma (continued). "Over the past two decades, several studies have assessed the association between CYP2A6 polymorphism, including whole-gene deletion of CYP2A6 on allele 4 (CYP2A6*4), and the risk of lung cancer among different ethnic populations, but the results have been inconsistent." (PMID 32547353, 2020). "Therefore, the present meta-analysis was performed to determine the association between CYP2A6 whole-gene deletion (CYP2A6*4) polymorphism and lung cancer risk." (PMID 32547353, 2020). "Investigating the role of CYP2A6 genotype in effective programs implemented for lung cancer screening may improve cancer risk prediction and assist selecting individuals who could benefit from preventative measures whether behavioural or pharmacological." (PMID 29724170, 2018). "The lower risk of lung cancer in Japanese Americans can in part be explained by their slower nicotine metabolism (measured by CYP2A6 activity), which has been shown to influence smoking intensity (measured by biomarkers of internal smoking dose) resulting in a lower exposure to tobacco carcinogens." (PMID 30139389, 2018). "Finally, we confirmed the association with lung cancer risk for rs4105144 upstream of CYP2A6 gene on chromosome 19, whose minor allele showed a protective role (OR < 1)." (PMID 28181565, 2017). "Additionally, CYP2A6 genetic variants are associated with lung cancer in a recent GWAS (Transdisciplinary Research in Cancer of the Lung (TRICL) consortium), even when controlling for smoking duration and quantity." (PMID 29194389, 2017). "Additionally, CYP2A6 plays a dual role in lung cancer risk among smokers via both indirect and direct mechanisms." (PMID 29194389, 2017). "We will also highlight the clinical relevance of variable CYP2A6 enzyme activity, as CYP2A6 variation is associated with smoking behavior, smoking cessation, tobacco-related lung cancer risk, and with altered metabolism and resulting clinical responses for several therapeutics." (PMID 29194389, 2017). "Thus, being a slower CYP2A6 metabolizer can reduce both tobacco consumption and procarcinogen activation, resulting in lower lung cancer risk." (PMID 29194389, 2017). "Further support for a direct effect can be found from studies, where after controlling for cigarette consumption (cigarettes per day and/or cigarette pack-years), CYP2A6 genotype reduced metabolizers, relative to normal metabolizers, continue to exhibit a decreased risk of having lung cancer." (PMID 29194389, 2017). "CYP2A6 activity should be further studied as a risk biomarker for smoking-related lung cancer." (PMID 28542511, 2017). "As variation in CYP2A6 activity is associated with smoking behavior, smoking cessation, tobacco-related lung cancer risk, and with altered metabolism and resulting clinical responses for several therapeutics, CYP2A6 expression and enzyme activity is an important clinical consideration." (PMID 29194389, 2017). "In post-hoc analyses of CYP2A6 SNPs, we observed nominally significant association with: abstinence in one pharmacotherapy arm; cigarette consumption among all trial participants; and lung cancer in four case:control studies." (PMID 26132489, 2015). "Individuals who possess the CYP2A6 His variant would be unable to activate procarcinogens in cigarette smoke and thus would be protected against cancer development, a finding that has been shown in lung cancer." (PMID 24651674, 2014). "Preferential enzymatic activation of distinct TSNAs, NNK by CYP2B6 and NNN by CYP2A6, may underlie the observed independent contributions of these genes to lung cancer risk." (PMID 23591849, 2013). "CYP2A6 polymorphisms are also associated with a variety of cancers, including lung cancer, gastric cancer, and bladder cancer, and the aromatase inhibitor letrozole is metabolized by CYP2A6 and is commonly used to treat hormone receptor-positive early breast cancer." (PMID 40860340, 2025).